PRSS51 (serine protease 51)
Gene: Protein-coding gene on chromosome 8 (10,482,878 to 10,547,624, reverse strand). Ensembl gene ENSG00000253649.
Subcellular location: Secreted
Gene Ontology:
Molecular function: serine-type peptidase activity; serine-type endopeptidase activity
Biological process: protein processing; proteolysis
Cellular component: plasma membrane; extracellular region
Homologues: Orthologues: macaque PRSS51 (95% identical), dog PRSS51 (74% identical), pig PRSS51 (71% identical), mouse Prss51 (70% identical), rat Prss51 (70% identical), zebrafish habp2 (23% identical), tropical clawed frog cfi (22% identical), zebrafish f9a (22% identical), Drosophila melanogaster CG31266 (19% identical), Drosophila melanogaster CG31267 (17% identical). Paralogues in human: PRSS55 (35% identical), F11 (30% identical), KLKB1 (30% identical), F7 (25% identical), F10 (24% identical), F9 (23% identical), HGFAC (23% identical), F12 (23% identical), CFD (22% identical), CFI (22% identical), KLK10 (22% identical), C1RL (21% identical), and 4 more.